FBLN2 (fibulin 2)
Diseases named in the same sentence as FBLN2 in open-access papers (continued):
Sharing a sentence is not in itself a finding about the gene and the disease.
breast carcinoma (continued). "Additionally, tumor susceptibility assays using mice lacking both Adamts12 and Fbln2 genes would be necessary to understand in depth the significance of this interaction not only in breast cancer but also in tumors from different origins." (PMID 24457941, 2014). "It is crucial, however, to disseminate the role of FBLN2 in tumor cells and BM/ECM at early versus advanced stages of breast cancer." (PMID 39110274, 2024). "Previous work in our laboratory has shown that the interaction between fibulin-2 and ADAMTS-12 promoted anti-tumor effects in breast cancer." (PMID 38396702, 2024). "In fact, fibulin-2 can be degraded by ADAMTS-4 and ADAMTS-5 under the same experimental conditions, which results in an increase of the tumoral properties of breast cancer cells." (PMID 33996918, 2021). "The interaction of ADAMTS-12 with fibulin-2 results in a blockade of the proteolytic degradation of fibulin-2 by ADAMTS4 and ADAMTS-5 and therefore, inhibition of the tumoral properties of breast cancer cells." (PMID 33996918, 2021). "It was reported that FBLN2 exerts a tumor suppressive function in nasopharyngeal cancer (NPC), breast cancer and gastric cancer." (PMID 34769264, 2021). "Presence of Fibulin-2 and ADAMTS-5 was also examined by western blot in a panel of eight paired normal-tumor breast cancer samples with the finding that an immunoreactive band corresponding to the metalloprotease was detected in all tumor samples." (PMID 28099917, 2017). "Overall, these results indicate that fibulin-2 and ADAMTS-12 affect ability of breast cancer cells to form mammospheres." (PMID 24457941, 2014). "Immunohistochemical detection of fibulin-2 and ADAMTS-12 was also performed using a human breast cancer tissue array." (PMID 24457941, 2014). "A moderate to strong expression of both fibulin-2 and ADAMTS-12 was detected in connective tissue surrounding tumor in grade 1 or 1 to 2 breast carcinoma (n=5)." (PMID 24457941, 2014). "Immunohistochemical staining of breast cancer samples allowed the detection of both ADAMTS-12 and fibulin-2 in the connective tissue surrounding tumor area in less aggressive carcinomas." (PMID 24457941, 2014). "Two breast cancer cell lines, MCF-7 and MDA-MB-231, were employed attending to the anti-tumor role of fibulin-2 and expression profile of ADAMTS12 in this type of tumor." (PMID 24457941, 2014). "In summary we have identified 5 (EMILIN2, SALL1, DBC1, FBLN2, CIDE-A) genes that demonstrated frequent tumour acquired methylation in breast cancer." (PMID 20205715, 2010). "Interestingly, the presence and interaction of fibulin-2 and ADAMTS-12 results in anti-tumor effects in breast cancer." (PMID 38396702, 2024). "Low perivascular fibulin-2 expression was strongly related to vascular invasion, low stromal elastosis, non-luminal breast cancer subtypes, interval presentation, and adverse prognosis." (PMID 33836007, 2021). "The role of FBLN2 in breast cancer has so far not been well studied and recent reports are contradictory about its contribution to tumour development." (PMID 30237579, 2018). "To investigate whether the presence of ADAMTS-12 could affect the behavior of breast cancer cells overexpressing ADAMTS-5, we carried out invasion assays using SK-BR-3 cells bearing in mind their endogenous expression of Fibulin-2." (PMID 28099917, 2017). "Thus, it can be inferred that simultaneous presence of Fibulin-2 and ADAMTS-5 can actively modify cellular behavior of breast cancer cells as well as the surrounding mammary fibroblasts, which represent a major and crucial component of tumor stroma." (PMID 28099917, 2017). "Similar results were obtained using T47D cells, other breast cancer cell line that does not express Fibulin-2." (PMID 28099917, 2017). "Our data using the poorly invasive breast cancer cell lines MCF-7 and T47D point out that protective role of Fibulin-2 could also be abolished through its degradation by ADAMTS-5." (PMID 28099917, 2017).
breast carcinoma (continued). "We have also investigated the localization of both Fibulin-2 and ADAMTS-5 in breast cancer samples as well as the effect that the conditioned medium of breast cancer cells that exogenously express Fibulin-2 alone or in combination with ADAMTS-5 produces on normal mammary fibroblasts." (PMID 28099917, 2017). "Interestingly, ADAMTS-12 was found to promote tumor development in breast cancer cells lacking FBLN2 by regulating metalloproteinase." (PMID 35445008, 2022). "Also, to our knowledge, there is no information on how fibulin-2 protein expression, in particular around vessel structures, relates to prognosis in breast cancer." (PMID 33836007, 2021). "Notably, the relationship between levels of fibulin-2, vascular invasion and detection mode (screen-detected versus interval breast cancer) has not been previously investigated." (PMID 33836007, 2021). "Consequently, the simultaneous presence of fibulin-1 and ADAMTS-1 or of fibulin-2 and ADAMTS-12 could be considered a good prognostic factor in breast cancer." (PMID 31508361, 2019). "Interestingly, the degradation of fibulin-2 by either ADAMTS-4 or ADAMTS-5 is blocked by the presence of ADAMTS-12 and seems to be a target for the protective role of the fibulin-2/ADAMTS-12 interaction in breast cancer." (PMID 31508361, 2019). "Although not fully conclusive, this indicates that FBLN2 may play different roles at the early and advanced stage of breast cancer progression." (PMID 30237579, 2018). "To this end, we used MCF-7 cells, a breast cancer cell line that does not express Fibulin-2." (PMID 28099917, 2017). "This regulation could extend to other pro-tumorigenic/pro-angiogenic genes that are regulated by α3β1, including fibulin-2 and MRP3 in MK cells, and COX-2 in breast cancer cells, as these genes harbor potential APA sites that in some cases flank canonical AREs within the 3’-UTR." (PMID 25751421, 2015). "The second relevant finding is that ADAMTS-12 could promote pro-tumor properties when is produced in breast cancer cells in the absence of fibulin-2." (PMID 24457941, 2014). "Such an invasive growth controlling role of FBLN2 would further be explained by the improved DMFS rate for breast cancer patients with LN negative or intermediate to low grade breast cancer, where the level of progression from DCIS to invasive growth could be the distinguishing factor." (PMID 30237579, 2018). "In breast cancer, ADAMTS12 can suppress tumorigenesis when interacts with fibulin-2, its chaperone protein, but can also promote tumor development if fibulin-2 is absent." (PMID 37642715, 2023).
nasopharyngeal carcinoma (12 papers, 2013 to 2024). A carcinoma arising from the nasopharyngeal epithelium. "In nasopharyngeal cancer, FBLN2 inhibits the metastatic properties via downregulation of vascular endothelial growth factor (VEGF) and matrix metalloproteinase 2 (MMP2), one of the ECM associated enzymes." (PMID 34769264, 2021). "It has been reported that the short form of FBLN2 is dominantly expressed in human nasopharyngeal carcinoma, breast, colon and lung cancer." (PMID 34769264, 2021). "In fact, the epigenetic regulation of FBLN2 with relation to tumor progression has been depicted in other types of human cancers, including childhood acute lymphoblastic leukemia and colon, prostate, breast and nasopharyngeal cancer." (PMID 34769264, 2021). "However, the Fibulin-2 protein has been described as a driver for malignant progression in lung adenocarcinomas, whereas the Fibulin 2 gene (FBLN2; chromosome 3p24-p25) has been reported to have tumour suppressive properties in nasopharyngeal carcinomas." (PMID 33429944, 2021). "In human nasopharyngeal carcinoma (NPC), the expression of fibulin-2 is down-regulated, suggesting its tumor-suppressive and anti-angiogenic role." (PMID 34063320, 2021). "For example, FBLN2 was found dramatically downregulated in NPC (nasopharyngeal carcinoma) and overexpression of FBLN2 inhibits cancer cell proliferation, migration, invasion, and angiogenesis in vitro." (PMID 24949431, 2014). "The FBLN2 short isoform was suggested to drive malignant progression in LUAD; however, in nasopharyngeal cancer, opposite results were reported." (PMID 25908786, 2015). "However, FBLN2 is a tumor suppressor in breast cancer and nasopharyngeal carcinoma (NPC)." (PMID 33194662, 2020).
lung adenocarcinoma (9 papers, 2013 to 2024). A carcinoma that arises from the lung and is characterized by the presence of malignant glandular epithelial cells. "On the basis of these findings, here we posited that fibulin-2 drives malignant progression by stabilizing tumor extracellular matrix and tested this hypothesis by performing correlative studies on human lung adenocarcinomas and loss-of-function experiments on KP cells." (PMID 23785517, 2013). "A similar mechanism has been proposed in lung adenocarcinoma, where FBLN2 can facilitate the development of the new ECM surrounding tumor cells, perhaps originating from tumor-associated fibroblasts." (PMID 39110274, 2024). "Elevated levels of fibulin-2 in the ECM of human lung adenocarcinomas, and in metastatic cells from a mouse model of a human lung adenocarcinoma underlined an important role of fibulin-2 as a promoter of lung cancer." (PMID 38396702, 2024). "Fibulin-2 promotes cross-linking of collagen and migration of tumour cells in primary lung adenocarcinoma, and it would be of interest to explore its role in the metastatic setting." (PMID 33836007, 2021). "Taken together, FBLN2 results in lung adenocarcinoma support an important role for this gene alternative splicing, as previously suggested." (PMID 25908786, 2015). "We conclude that fibulin-2 is a driver of malignant progression in lung adenocarcinoma and plays an unexpected role in collagen cross-linking and tumor cell adherence to collagen." (PMID 23785517, 2013). "Fibulin-2 was quantified by immunohistochemical analysis of 46 primary lung adenocarcinomas and adjacent lung tissues." (PMID 23785517, 2013). "Fibulin-2 was abundantly expressed in metastatic cells from a mouse model of human lung adenocarcinoma and was required for metastatic behaviors of these cells." (PMID 23785517, 2013). "In human lung adenocarcinoma, FBLN2 shows both ‘fibrillar’ and ‘fibrotic’ expression patterns, indicating that FBLN2 might have multiple cellular origins and biological functions." (PMID 34769264, 2021). "We examined whether fibulin-2 is expressed in human lung adenocarcinomas." (PMID 23785517, 2013). "We showed that fibulin-2 was abundant in the extracellular matrix of human lung adenocarcinomas and was distributed in two different intra-tumoral patterns, “fibrillar” and “fibrotic”, suggesting that fibulin-2 may have multiple cellular origins and biological roles." (PMID 23785517, 2013). "Nevertheless, FBLN2 plays an oncogenic role in head and neck squamous cell carcinoma (HNSCC) and murine lung adenocarcinoma." (PMID 34769264, 2021). "As opposed to breast, colon and thyroid adenocarcinoma, no significant expression change was observed for FBLN2 in lung adenocarcinoma and it is the only cancer type in which a significant correlation of PSI change and cancer survival was observed." (PMID 25908786, 2015).
lung cancer (8 papers, 2010 to 2025). A malignant neoplasm involving the lung. "After application of a urethane protocol to induce lung carcinoma, we observed that mice deficient in fibulin-2 and ADAMTS12 showed a higher incidence of lung carcinomas than their corresponding wild-type littermates." (PMID 38396702, 2024). "Taken together, our data suggest that downregulation of FBLN2 in lung cancer cell lines may be associated with DNA methylation and histone acetylation." (PMID 34769264, 2021). "At the same time, several genes downregulated in NPRL2−/− cells are also known to be downregulated in lung cancer (FBLN2, LBH, AMPH-1), glioblastoma (ELAVL2), and liver cancer (IGFBP4)." (PMID 41469472, 2025). "Differences in fibulin-2 expression in the tumoral processes have been described in breast, pancreatic and lung cancers, among others." (PMID 38396702, 2024). "Cell-based assays showed the functional importance of fibulin-2 promoter methylation in the cell proliferation, migration, and invasion properties of lung cancer cell lines, and suggest a tumor-suppressive role for fibulin-2 in human cells." (PMID 38396702, 2024). "Further regulation of fibulin-2 expression, through promoter methylation events, has been described in breast and lung cancers." (PMID 38396702, 2024). "We focused our studies on the double knock-out mice in a lung cancer model since the fibulin-2-/-/Adamts12-/- mice presented significant lesions in the lung parenchyma." (PMID 38396702, 2024). "For this purpose, we chemically induced lung carcinoma following the intraperitoneal injection of urethane model to study the effects on fibulin-2/Adamts12 mutant mice." (PMID 38396702, 2024). "Fibulin2 (FBLN2) is decreased in the lung cancer cell lines, and the overexpression of FBLN2 would inhibit the activation of MAPK/ERK and AKT/mTOR signaling pathways, accompanied by the decreased migration and invasion of cells." (PMID 36033435, 2022). "Altogether, these results suggest that FBLN2 has the potential to inhibit lung cancer cell proliferation." (PMID 34769264, 2021). "FBLN2′s expression pattern indicated that it was downregulated in a majority of lung cancer cell lines compared to normal cell line and the short isoform was found to be the main expression form in lung cells, consistent with a previous report." (PMID 34769264, 2021). "FBLN2 isoforms exhibit a dramatic expression shift during tumorigenesis in nine different cancers, including lung cancer." (PMID 34769264, 2021). "In this study, we found that FBLN2 was downregulated in 9 out of 11 lung cancer cell lines compared to normal bronchial epithelial cells, which was associated with DNA hypermethylation." (PMID 34769264, 2021). "FBLN2 was widely restored in all lung cancer cell lines on the mRNA level except H23 and H1975 and increased in H157, H2030 and A549 on the protein level." (PMID 34769264, 2021). "Compared to HBEC, FBLN2 was downregulated in 9 or 10 out of 11 lung cancer cell lines on the mRNA or protein level." (PMID 34769264, 2021). "Our data showed that FBLN2 DNA was methylated in the promoter region in most of the lung cancer cell lines displaying downregulated FBLN2, implying that DNA methylation is a frequent epigenetic event partially responsible for FBLN2 gene silencing." (PMID 34769264, 2021). "Knockdown of the FBLN2 gene in lung cancer cells inhibited tumor growth and lymph node metastatic properties in a xenograft and orthotopic 129/SV mice model." (PMID 33194662, 2020). "In summary, the generation of mice deficient in fibulin-2 and ADAMTS-12 contributed to the in vivo validation that the interaction between these two proteins has an antitumor role in lung cancer and has an effect in modulating the immune response after lung injury." (PMID 38396702, 2024). "The cancer growth inhibitory role of FBLN2, as revealed in this study, may provide a basis for further exploring its therapeutic value in human lung cancer." (PMID 34769264, 2021).
lung cancer (continued). "Additionally, samples with lower T stage tumors tended to have higher FBLN2 expression, providing clues to its possible tumor suppressive function in lung cancer." (PMID 34769264, 2021). "Furthermore, the bisulfite sequencing and methylation-specific-PCR (MSP) were applied to analyze the methylation status of FBLN2 promoter in both lung cancer cell lines and tumor tissues." (PMID 34769264, 2021). "In all, our data suggest that FBLN2 may suppress lung cancer cell proliferation through regulating MAPK/ERK and PI3K/AKT/mTOR pathways." (PMID 34769264, 2021). "They found that FBLN2 was abundant in the ECM of human lung cancer." (PMID 33194662, 2020). "However, there is limited knowledge about the function of FBLN2 in human lung cancer, and the regulatory role of FBNL2 in cell adhesion and ECM construction in human lung cancer is also largely unknown." (PMID 34769264, 2021). "In addition to DNA methylation, histone acetylation might also play a role in the downregulation of FBLN2, since enhanced levels of FBLN2 were also detected in six out of nine lung cancer cell lines after treatment with TAS, a histone deacetylase inhibitor." (PMID 34769264, 2021). "DNA methylation of FBLN2 in lung cancer cell lines was confirmed by MSP, confirming the utility of MSP for the analysis of the methylation status of FBLN2 in tissue samples." (PMID 34769264, 2021). "A variable FBLN2 DNA methylation was found in lung cancer cell lines, whereas no methylation of FBLN2 DNA was detected in control HBEC." (PMID 34769264, 2021). "In primary lung cancer tissues, 44.2% (46/104) of tumor samples exhibited negative staining of the Fibulin 2 protein, and SCC samples displayed significantly higher expression of FBLN2 than ADC, indicating its potential diagnostic value for distinguishing lung SCC from ADC." (PMID 34769264, 2021).
myocardial infarction (6 papers, 2013 to 2024). Gross necrosis of the myocardium, as a result of interruption of the blood supply to the area, as in coronary thrombosis. "The distinctive characteristic of Fbln2 renders it a promising therapeutic target for the prevention of progressive ventricular dysfunction following myocardial infarction." (PMID 39456238, 2024). "Loss of FBLN2 has been suggested to attenuate angiotensin-II signaling via a reduction of TGFβ1 activation and can further protect against ventricular dysfunction in FBLN2-null mice after myocardial infarction." (PMID 33003281, 2020).
breast tumor (5 papers, 2010 to 2024). "The present study indicates a strong association between fibulin-2 expression and high amount of elastotic stroma in breast tumours." (PMID 33836007, 2021). "In fact, Fibulin-2 can act as a physical barrier hampering the dissemination of cancer cells in breast tumors and thereby loss of its expression has been associated with progression of cancer cells." (PMID 28099917, 2017). "However, using a panel of breast tumor cell lines it has been shown that the loss of expression of fibulin-2 is related to a greater tumor progression, which suggests its role as a tumor suppressor." (PMID 38396702, 2024). "Six breast tumor samples corresponding to advanced stages of the disease were additionally analyzed and a weak signal corresponding to the entire Fibulin-2 was detected in three samples and ADAMTS-5 was identified in most of them." (PMID 28099917, 2017). "Thus, fibulin-2 could be considered as a tissue and plasma biomarker of breast tumors." (PMID 38396702, 2024). "Immunohistochemical analysis highlights the close proximity or partial overlap of both Fibulin-2 and ADAMTS-5 in breast tumor samples." (PMID 28099917, 2017). "Using a combination of COBRA and sequencing of bisulphite modified DNA, we confirmed 5 novel genes frequently methylated in breast tumours; EMILIN2, SALL1, DBC1, FBLN2 and CIDE-A." (PMID 20205715, 2010). "In this scenario and in the absence of fibulin-2, ADAMTS-12 could contribute to tumor progression by increasing the migratory capacity of breast tumor cells on collagen-1." (PMID 24457941, 2014).